TRDN (triadin)
Description:
Contributes to the regulation of lumenal Ca2+ release via the sarcoplasmic reticulum calcium release channels RYR1 and RYR2, a key step in triggering skeletal and heart muscle contraction. Required for normal organization of the triad junction, where T-tubules and the sarcoplasmic reticulum terminal cisternae are in close contact (By similarity). Required for normal skeletal muscle strength. Plays a role in excitation-contraction coupling in the heart and in regulating the rate of heart beats.
Synonyms: TRISK; CARDAR; CPVT5; TDN
Tractability: Antibody: UniProt places it where antibodies can reach, with high confidence; its Gene Ontology location is reachable by antibodies, with high confidence; UniProt predicts a signal peptide or a membrane-spanning region. PROTAC: ubiquitination databases record sites on it.
Gene: Protein-coding gene on chromosome 6 (123,215,088 to 123,637,260, reverse strand). Ensembl gene ENSG00000186439.
Subcellular location: Cell membrane; Sarcoplasmic reticulum membrane
Subcellular location (Human Protein Atlas): Cytosol; Plasma membrane; Nucleoplasm
Pathways (Reactome):
Muscle contraction: Ion homeostasis
Transport of small molecules: Stimuli-sensing channels
Gene Ontology:
Molecular function: protein binding; protein-macromolecule adaptor activity; transmembrane transporter binding; signaling receptor binding
Biological process: heart contraction; cytoplasmic microtubule organization; endoplasmic reticulum membrane organization; intracellular calcium ion homeostasis; muscle contraction; positive regulation of cell communication by electrical coupling involved in cardiac conduction; regulation of cardiac muscle cell membrane potential; regulation of cardiac muscle contraction by regulation of the release of sequestered calcium ion; regulation of cell communication by electrical coupling; regulation of release of sequestered calcium ion into cytosol by sarcoplasmic reticulum; release of sequestered calcium ion into cytosol by sarcoplasmic reticulum
Cellular component: plasma membrane; sarcoplasmic reticulum membrane; endoplasmic reticulum; junctional membrane complex; junctional sarcoplasmic reticulum membrane; membrane; sarcoplasmic reticulum; sarcoplasmic reticulum lumen
Genetic constraint (gnomAD): Loss-of-function variants: 65 observed, 58.78 expected, observed/expected ratio (o/e) 1.11, 90% interval 0.9 to 1.36. The upper end of that interval is the gene's LOEUF score, 1.36, which puts it in group 5 of 6, group 1 being the genes least tolerant of losing a copy. Missense variants: 497 observed, 435.7 expected, observed/expected ratio (o/e) 1.14, 90% interval 1.06 to 1.23. Synonymous variants: 179 observed, 145.02 expected, observed/expected ratio (o/e) 1.23, 90% interval 1.09 to 1.4.
Gene-disease validity (ClinGen):
ClinGen rates the evidence that TRDN causes each of these diseases.
catecholaminergic polymorphic ventricular tachycardia (autosomal recessive): Definitive. Catecholaminergic polymorphic ventricular tachycardia (CPVT) is a severe genetic arrhythmogenic disorder characterized by adrenergically induced ventricular tachycardia (VT) manifesting as syncope and sudden death.
long QT syndrome (autosomal recessive): Strong.
Homologues: Orthologues: chimpanzee TRDN (98% identical), macaque TRDN (95% identical), dog TRDN (85% identical), pig TRDN (85% identical), rabbit TRDN (80% identical), guinea pig TRDN (73% identical), mouse Trdn (67% identical), rat Trdn (65% identical), zebrafish si:ch211-266g18.10 (32% identical), zebrafish trdn (17% identical).
Diseases named in the same sentence as TRDN in open-access papers:
TRDN is named in the same sentence as 47 diseases in open-access papers, as found by Europe PMC text mining. Sharing a sentence is not in itself a finding about the gene and the disease. The quoted sentences say what the papers report.
catecholaminergic polymorphic ventricular tachycardia (8 papers, 2015 to 2025). "In this study, we report a novel pathogenic variant of the TRDN gene, and catecholaminergic polymorphic ventricular tachycardia (CPVT) associated with sinus bradycardia in 2 siblings from a consanguineous Malian family." (PMID 40760564, 2025). "Triadin-1, encoded by TRDN, is an important component of the calcium release unit in the sarcoplasmic reticulum of cardiac myocytes and a number of variants have been identified in patients with catecholaminergic polymorphic ventricular tachycardia (CPVT)." (PMID 33895855, 2021). "Both of them are regulators of RyR2 and mutations in both triadin and calmodulin have been associated with catecholaminergic polymorphic ventricular tachycardia, a rare familial arrhythmogenic disorder characterized by maligant ventricular arrhythmias and increased risk of SCD." (PMID 26196381, 2015). "Catecholaminergic polymorphic ventricular tachycardia (CPVT) is a stress-induced ventricular arrhythmia associated with cytoplasmic calcium leakage due to mutations in calsequestrin 2 (CASQ2), ryanodine receptor (RyR2), triadin, or calmodulin." (PMID 33329039, 2020). "The hereditary pro-arrhythmic condition catecholaminergic polymorphic ventricular tachycardia (CPVT), is associated with gene mutations involving ryanodine receptor type 2 (RYR2), calsequestrin (CASQ2), triadin (TRDN) or calmodulin (CALM1, CALM2 and CALM3)." (PMID 34643236, 2021).
Arrhythmia (4 papers, 2020 to 2025). Any cardiac rhythm other than the normal sinus rhythm. "Although TRDN loss is associated with tachycardia in patients with TKOS, in Trdn−/− mice, the electrocardiogram (ECG) evaluation demonstrated sinus bradycardia and Triadin overexpression was proven to predispose rat cardiac myocytes to arrythmia." (PMID 34575879, 2021). "Three years later, the term “Triadin KnockOut Syndrome (TKOS)” was proposed as a syndrome leading to high risk of arrhythmias caused by homozygous TRDN alterations, mainly in infants and young populations." (PMID 33692971, 2020). "Lastly, based on our observations in SANAD, we note that variation in some genes like PRKCZ or TRDN may lead to susceptibility of secondary symptoms (in epilepsy or other neurodevelopmental disorders) e.g., memory loss or arrhythmia." (PMID 41345172, 2025). "Trdn knock-out mouse models suffered from cardiac arrhythmias and skeletal muscle weakness, thus indicating that Triadin is involved in cardiac and skeletal muscle function." (PMID 34575879, 2021).
Ventricular arrhythmia (3 papers, 2015 to 2026). "In people, TRDN mutations are linked to a genetic form of ventricular arrhythmia, and ablation of TRDN renders the hearts susceptible to ventricular arrhythmias." (PMID 41488471, 2026).
channelopathy (2 papers, 2021 to 2024). Channelopathies are a group of diseases caused by the dysfunction of ion channel subunits or their interacting proteins. "NGS revealed the index case was heterozygous for three additional low-frequency variants in channelopathy-associated genes that are more frequent in Latinos: SCN5A p.V1951L (rs41315493), ANK2 p.G2221E (rs185384934) and TRDN p.S80F (rs181287533)." (PMID 38256028, 2024). "Out of these 10 cases, 1 individual (2.2%) carried a pathogenic variant in the cardiomyopathy-associated gene DTNA and 2 individuals (4.4%) carried 2 (1 pathogenic and 1 likely pathogenic) variants in the channelopathy-associated genes SCN5A and TRDN, respectively." (PMID 33895855, 2021).
long QT syndrome 3 (2 papers, 2021 to 2025). An autosomal dominant condition caused by mutation(s) in the SCN5A gene, encoding sodium channel protein type 5 subunit alpha. "IRS1 is also involved in the development of coronary heart diseases, whilst the TRDN gene is involved in other forms of heart failure, ventricular tachycardia, and Romano-Ward Syndrome." (PMID 33924951, 2021).
Parkinson disease (2 papers, 2021). A progressive degenerative disorder of the central nervous system characterized by loss of dopamine producing neurons in the substantia nigra and the presence of Lewy bodies in the substantia nigra and locus coeruleus. "Furthermore, in the previous study, we observed decreased expression of TRDN in muscle in a mouse model of Parkinson’s disease." (PMID 34736417, 2021).
Sinus bradycardia (2 papers, 2021 to 2025). Bradycardia related to a mean resting sinus rate of less than 50 beats per minute. "In this report, we describe 2 siblings from a consanguineous Malian family who were diagnosed with CPVT with sinus bradycardia associated with a novel pathogenic homozygous variant in the TRDN gene." (PMID 40760564, 2025).
Bradycardia (1 paper, 2025). A slower than normal heart rate (in adults, slower than 60 beats per minute). "Although bradycardia has been previously reported in patients with RYR2 variants, its presence in individuals with CPVT due to TRDN variants, as shown in this report, is not well documented." (PMID 40760564, 2025).
cardiac arrest (1 paper, 2021). Cessation of breathing and/or cardiac function. "When the proband was initially diagnosed with CPVT following her cardiac arrest, exons of RyR2 encompassing hot spot mutations and all coding exons of CASQ2 and TRDN were first screened, but no variant was found." (PMID 34202968, 2021).
hyperlipidemia (1 paper, 2022). "Analysis of upregulated DEGs has shown that the following seven genes were common between all complications of TIDM (hyperlipidemia, neuropathy, ketoacidosis, hypothyroidism and PCOS): SPINK9, TRDN, PVRL4, MYO3A, PDLIM1, KIAA1614 and GRP." (PMID 36175575, 2022).
idiopathic ventricular fibrillation (1 paper, 2024). "Genetic testing is recommended for CPVT-susceptibility genes—RyR2, CASQ2, CALM1-3, TRDN and TECRL—in all probands with a definitive clinical diagnosis of CPVT and may be considered in individuals with idiopathic ventricular fibrillation (VF) upon identification of an adrenergic trigger." (PMID 38542006, 2024).
long QT syndrome (1 paper, 2021). "Recent studies have shown that Ca2+ binding proteins such as calmodulin, and triadin, are associated with the long QT syndrome." (PMID 34820430, 2021).
morbid obesity (1 paper, 2024). An excess of body weight, normally defined as an individual with a body mass index greater than 35 or a body weight greater than one hundred percent of ideal body weight. "Furthermore, a recent study showed that TRDN was upregulated in SAT of humans with morbid obesity and type II diabetes mellitus as compared with nondiabetic, body mass index (BMI)-matched individuals further implicating a role for triadin in disease progression in AT." (PMID 39348460, 2024).
myasthenia (1 paper, 2022). "The TRDN gene was related to autosomal recessive catecholamine-sensitive ventricular tachycardia type 5 with or without myasthenia (OMIM:615,441), but it was generally caused by homozygous or compound heterozygous mutations." (PMID 35590339, 2022).
neuropathy (1 paper, 2022). A disorder affecting the nervous system that manifests with pain, tingling, numbness, and/or muscle weakness. "As shown in Boxplots 8A and 8B, KIAA1614 and TRDN were significantly upregulated in neuropathy (p < 0.05)." (PMID 36175575, 2022).
Obesity (1 paper, 2024). Accumulation of substantial excess body fat. "Similar to our observations in VAT of obese mice, the expression of trdn was also shown to be substantially upregulated in skeletal muscle of Caucasian women with obesity, however, a specific role for triadin was not investigated." (PMID 39348460, 2024).
Skeletal myopathy (1 paper, 2018). "Recessive frameshift mutations, leading to loss of TRDN, were found to cause a skeletal myopathy in a subsetof patients with triadin knockout syndrome." (PMID 30631434, 2018).
myopathy (4 papers, 2016 to 2022). A disease of the muscle in which the muscle fibers do not function properly. "Moreover, there is no information regarding TRDN mutations in patients affected by myopathy without heart function dysregulation." (PMID 34575879, 2021). "Since both authors make valid points, whether or not the absence of triadin results in a RyR1 myopathy has yet to be determined." (PMID 27855725, 2016).
cancer (2 papers, 2022 to 2024). A tumor composed of atypical neoplastic, often pleomorphic cells that invade other tissues. "The study reported that the potential muscle-specific genes expressed in cancer cells were TNNI1, TNNT1, DES, TRDN, MYH6, MYH11, and MYH13." (PMID 36378654, 2022).
heart disease (1 paper, 2022). "In contrast to heart muscle, where mutations in triadin are associated with heart disease, no skeletal muscle disease has been associated with triadin so far." (PMID 35454077, 2022).
TRDN also shares sentences with these, for which no sentence is quoted: ventricular tachycardia (2 papers); Andersen-Tawil syndrome (1); arrhythmogenic right ventricular cardiomyopathy (1); breast carcinoma (1); Brugada syndrome (1); cardiac arrhythmias (1); cardiomyopathy (1); chronic heart failure (1); coronary heart diseases (1); diabetes (1); dilated cardiomyopathy (1); epilepsy (1); essential hypertension (1); familial hypercholesterolemia (1); glycogenosis (1); heart failure (1); Hypertension (1); hypothyroidism (1); lung adenocarcinoma (1); neurodevelopmental disorder (1); sudden cardiac arrest (1); Timothy syndrome (1); torsades de pointes (1); tumour (1); type 2 diabetes mellitus (1); Vascular Ehlers-Danlos Syndrome (1); ventricular fibrillation (1).